EZH2 (enhancer of zeste 2 polycomb repressive complex 2 subunit)
Diseases named in the same sentence as EZH2 in open-access papers (continued):
Sharing a sentence is not in itself a finding about the gene and the disease.
neurodegenerative disease (6 papers, 2013 to 2024). A disorder of the central nervous system characterized by gradual and progressive loss of neural tissue and neurologic function. "In the field of neurodegenerative diseases, studies demonstrated an upregulation of EZH2 in the brains of PD patients, suggesting its possible pathogenic role in PD progression." (PMID 37391829, 2023). "Together, our results support Smurf2 as a regulator of EZH2 turnover to facilitate PPARγ expression, which is specifically required for neuron differentiation, providing a molecular mechanism for clinical applications in the neurodegenerative diseases." (PMID 23526793, 2013).
benign tumors (5 papers, 2011 to 2021). "The clear cell type of benign tumours had the highest proliferation fraction, and the plasmacytoid cell type showed a higher percentage of EZH2 positive cells." (PMID 21917131, 2011). "We have described that EZH2 is expressed in most of the malignant liver tumors, but it is absent from the benign tumors and reactive proliferative lesions." (PMID 26377323, 2015). "Besides, the expression of EZH2 mRNA was higher in LMS and RMS than in benign tumors (p < 0.05)." (PMID 30120321, 2018).
gastrointestinal tumors (5 papers, 2021 to 2025). "First, our qRT-PCR results demonstrated that EZH2 was differentially expressed at the transcriptomic level in four gastrointestinal tumors, including LIHC, STAD, COAD, PAAD." (PMID 36545914, 2023). "Moreover, we also performed the IHC experiments to compare the protein levels of EZH2 in various digestive system tumors." (PMID 36545914, 2023). "Importantly, our observations uncover a novel ubiquitination cascade composed of UBA6, UBE2Z, and FBXW7 that may regulate the degradation of the squamocin‐induced EZH2/MYC axis in pan‐gastrointestinal tumors." (PMID 39823459, 2025).
blood cancers (4 papers, 2019 to 2024). "As observed in solid tumors, in hematological neoplasms, there is also an association between c-Myc deregulation and EZH2 overexpresion." (PMID 31886200, 2019). "Solid tumors often overexpress EZH2, whereas hematologic neoplasms show a more diverse picture of how EZH2 is altered." (PMID 34947882, 2021). "The role of enhancer of zeste homolog 2 (EZH2) in blood cancers is not well understood." (PMID 38339323, 2024). "Moreover, in blood cancers, inactivating mutations of EZH2 with TET2 have been observed in patients with myelodysplastic disorders, while in vivo deletion of EZH2 could increase the expression of “Myc module” genes and lead to myelodysplastic phenotypes." (PMID 38036730, 2023).
immune diseases (4 papers, 2016 to 2022). "Although EZH2 appears to function as a pivotal immune regulator, how EZH2 affects the progress of inflammatory and immune diseases such as IBD remains poorly understood." (PMID 31160593, 2019). "Accumulating evidence shows that EZH2 has critical roles in T cells and could be a promising therapeutic target for several immune diseases." (PMID 27468692, 2016). "The inhibition of EZH2 could alleviate ATII apoptosis and decrease A549 proliferation, which might be a potential clinical treatment with which to modulate immune disorders." (PMID 36552722, 2022).
neurodevelopmental disorder (4 papers, 2022 to 2025). A behavioral and cognitive disorder with onset during the developmental period that involves impaired or aberrant development of intellectual, motor, or social functions. "To date, however, no study has investigated the specific in vivo roles of neuronal EZH2 in neural development, which might be more relevant to neurodevelopmental disorders." (PMID 37326884, 2023).
psychiatric diseases (4 papers, 2018 to 2022). "EZH2, a histone methyltransferase, is critical in the process of cellular development, immune system and neuronal function of psychiatric diseases." (PMID 35172677, 2022).
infectious disease (3 papers, 2022 to 2025). A disorder directly resulting from the presence and activity of a microbial, viral, or parasitic agent in humans. "Specific inhibitors of EZH2, such as tazemetostat, may thus be effective co‐treatment options along antivirals used in treatment of COVID‐19 and other infectious diseases." (PMID 35833542, 2022). "LncRNA PINT serves as a molecular scaffold linking p65 and enhancer of zeste homolog 2 (EZH2) to regulate the transcription of inflammatory factors, highlighting the importance of this lncRNA as a potential therapeutic target in infectious diseases." (PMID 41156681, 2025).
bacterial infection (2 papers, 2021 to 2022). "Thus, we demonstrate complex and opposing effects of EZH2 deficiency in monocytic lineage cells, in which we observe an enhanced proinflammatory responses of macrophages, while loss of EZH2 in neutrophils impairs migration and responses to bacterial infection." (PMID 34464475, 2021). "In order to show that neutrophil Ezh2 was essential to combat bacterial infection of the lung, we used this adoptive transfer model to test responses to intranasal infection with S pneumoniae." (PMID 34464475, 2021). "As EZH2 played such a major role in the macrophage response to bacterial infection, we extended these studies to include the myeloid lineage more generally, as in the neutrophil population EZH2 is reported to exert a nongenomic role in cytoskeletal function, and motility." (PMID 34464475, 2021).
cardiac disease (2 papers, 2022 to 2023). "In addition, EZH2 increases susceptibility to fibrosis in pathological processes, and that inhibition of EZH2 has the potential to reverse the fibrotic phenotype in cardiac disease." (PMID 35954191, 2022). "Given the partial functional redundancy between EZH1 and EZH2, additional studies into the role of EZH1 in these cardiac disease models is warranted, especially as a potential therapeutic target to offer protection following cardiac injury." (PMID 37504561, 2023).
gynecological disease (2 papers, 2020 to 2022). "In OC, the most lethal gynecological disease, EZH2 also serves as a booster for the invasion and migration of OC cells." (PMID 33292225, 2020). "It is also tempting to postulate that a combination of EZH2 inhibitors and inflammatory modulators may be a possible approach to combat this most common gynecological disease." (PMID 35269532, 2022).
metabolic disorders (2 papers, 2022 to 2024). "Increased expression of EZH2 seems to be associated with metabolic disorders since mTORC1-mediated glycolysis controls EZH2 expression in SLE T cells, suggesting that glycolytic pathways might be indirect targets for suppressing EZH2 expression." (PMID 36220996, 2022). "Our finding supports the hypothesis that EZH2 represents a potential pharmacological target for addressing metabolic disorders." (PMID 39408226, 2024).
digestive system cancer (1 paper, 2023). A primary or metastatic malignant neoplasm involving any part of the digestive system. "Since gastrointestinal malignancies are the most prevalent tumors, verifying the differential expression of EZH2 in digestive system cancers is the focus of the rest of the present study." (PMID 36545914, 2023).
respiratory diseases (1 paper, 2023). "In recent years, there are more and more reports on non-coding RNA in respiratory diseases, but the role and mechanism of SNHG4 in regulating the miR-144-3p/EZH2 axis in COPD and bronchial epithelial cells have not been reported at home and abroad." (PMID 38114929, 2023).
vasculopathy (1 paper, 2021). "To determine whether EZH2 is implicated in the obliterative vasculopathy that characterized PAH, we first measured its protein expression level in lungs, dissected PAs (<1000 μm in diameter), and isolated PASMCs from control and PAH patients." (PMID 33803922, 2021).
EZH2 also shares sentences with these, for which no sentence is quoted: Cohen-Gibson syndrome (8 papers); idiopathic pulmonary fibrosis (8); Sotos syndrome (7); adult T-cell leukemia (6); acute leukemia (5); Imagawa-Matsumoto syndrome (4); endometrial tumors (3); endometrioid carcinoma (3); fibrosarcoma (3); gastrointestinal stromal tumor (3); inflammation (3); Nephropathy (3); pancreatitis (3); Tatton-Brown-Rahman syndrome (3); acral melanoma (2); actinic keratosis (2); Allergy (2); B-cell acute lymphoblastic leukemia (2); CHARGE syndrome (2); childhood tumors (2); clear cell sarcoma of the kidney (2); CNS tumors (2); Cutaneous T-cell Lymphoma (2); dengue (2); epithelial ovarian cancer (2); genetic disease (2); Head and neck tumors (2); Impaired glucose tolerance (2); inflammatory breast carcinoma (2); intervertebral disc degeneration (2).
A further 164 diseases each share a sentence with EZH2 in 2 papers or fewer.